KRAS (KRas proto-oncogene, GTPase)
Diseases named in the same sentence as KRAS in open-access papers (continued):
Sharing a sentence is not in itself a finding about the gene and the disease.
metastatic disease (continued). "There was a significant correlation between the extension of disease and exosomes level and the resection of primary localized tumor was correlated with a decrease of KRAS G12V/ D copies and fractional abundance in metastatic disease." (PMID 34811396, 2021). "The evaluation of KRAS mutation status in CRC patients has a crucial prognostic role, since patients carrying KRAS mutations have a poor response to anti-EGFR therapy and show an increased cumulative incidence of metastatic disease." (PMID 32676506, 2020). "We show that loss of KRAS and SMAD4 mutations characterizes the oligo-metastatic disease while a progressive mutational evolution (gain in KRAS, PI3KCA, BRAF and SMAD4) is observed in poly-metastatic evolving disease." (PMID 33096795, 2020). "After next-generation sequencing technology has been established and more widely available, more studies were conducted to evaluate KRAS heterogeneity between primary and metastatic tumors." (PMID 33002027, 2020). "The rationale for the application of anti-EGFR monoclonal antibodies in KRAS exon 2 wt MCC cases depended on the appropriate concordance of mutational status between primary and metastatic tumours, as presented in previous literature." (PMID 30683047, 2019). "All polymorphisms detected were also significantly associated with the metastatic disease (p<0.001) leading to shorter overall survival (p<0.001); whereas, TLR4 Asp299Gly and Thr399Ile polymorphisms were significantly associated with KRAS mutations." (PMID 29883450, 2018). "Current research is focusing on both KRAS and BRAF as predictive and diagnostic biomarkers in patients with metastatic disease treated with anti-EGFR therapies, such as panitumumab and cetuximab." (PMID 28097409, 2017). "KRAS testing was performed in 35.1% of CRCs and as expected was more frequent in patients with a metastatic disease (65.5%)." (PMID 29137623, 2017). "The results also expose CD147 as a potential CSC-specific target in the context of the metastatic disease of KRasG12V-driven cancers and are indicative of the oncogenic KRas-impelled stemness and therapeutic resistance." (PMID 27894102, 2016). "Distribution according to extension of metastatic disease, L-L and O/MM, was, respectively: KRAS wild-type, 3 (14%) and 18 (86%); KRAS mutant, 6 (35%) and 11 (65%)." (PMID 24247407, 2014). "More than half (n = 18) indicated that they ordered the KRAS test when the cancer became metastatic or during first-line treatment for metastatic disease." (PMID 24403261, 2013). "Another possible bias in our study is the imbalance observed in some parameters between patients with WT and MT KRAS tumours (prior adjuvant therapy and surgery for metastatic disease prior to the study entry)." (PMID 23174912, 2012). "Patients' distribution according to extension of metastatic disease, L-L and O/MM, was, respectively: overall, 25 (42%) and 34 (58%); KRAS wild-type, 12 (39%) and 19 (61%); KRAS mutant, 13 (46%) and 15 (54%)." (PMID 23136868, 2012). "The number of MCRC patients with KRAS wild-type and mutant genotypes was 31 (53%) and 28 (47%), respectively; the male/female ratio was 21/10 and 16/12; synchronous metastatic disease, 21 (68%) and 21 (75%) patients." (PMID 23136868, 2012). "We verified previously reported findings of significantly different outcome (PFS and OS) with FIr-B/FOx according to extension of metastatic disease in KRAS wild-type and mutant patients." (PMID 23136868, 2012).
metastatic disease (continued). "Increased expression of KRAS protein was more frequent in squamous cell carcinomas and in lymph node metastasis compared to non-metastatic tumors (34 vs. 20 or 56.7 % vs. 33.3 %; P = 0.01)." (PMID 22537942, 2012). "TOPK expression is an unfavourable prognostic indicator in sporadic patients with KRAS or BRAF mutations and also in patients with metastatic disease experiencing a response to anti-EGFR therapies." (PMID 19935791, 2010). "In conclusion, TOPK seems to be a valuable prognostic factor in patients with sporadic CRC with KRAS or BRAF gene mutations, as well as in patients with metastatic disease who respond to anti-EGFR therapies." (PMID 19935791, 2010). "Depending on the availability of funding, it would be optimal for KRAS testing to begin immediately following a diagnosis of metastatic disease; currently however, testing can only be undertaken when the Oncologist is considering third-line therapy." (PMID 20680106, 2010). "Specifically, we observed disparities in the prevalence of metachronous versus synchronous metastatic disease, as well as variations in the location-dependent metastatic sequence, Pn and V status, applications of systemic chemotherapy (CTX), and KRAS mutational status." (PMID 39594697, 2024). "We demonstrated that both the primary and matched metastatic tumors harbored identical KRAS (3/4) and PTEN (1/4) mutations, and did not harbor any additional mutations." (PMID 37626765, 2023). "Median OS survival was longer in all patients who had undergone metastatic tumor resection than in those who did not undergo surgery, independently of the codon location of the KRAS mutation or the primary tumor location." (PMID 37141400, 2023). "P2 had a liver metastatic site resected before ctDNA testing, and the metastatic tumor tested negative for KRAS mutation." (PMID 37511664, 2023). "Consistent with our result, in one case, both the primary and metastatic tumors harbored an identical KRAS mutation, without additional mutations." (PMID 37626765, 2023). "For patients with metastatic disease, the outcome largely depends on the identification of a targetable driver such as EGFR, ALK, ROS1, ERBB2, BRAF, MET and more recently KRAS, RET, NRG1 and NTRK1-2-3, as mutations or gene fusions are highly predictive of response to matched targeted therapy." (PMID 35326552, 2022). "KRAS and BRCA2 mutations were found in both primary and metastatic tumors." (PMID 35666369, 2022). "Notably, PAT2 and PAT5 had lymphocytes with the highest T cell-mediated cytotoxic activity against SW620 cells (p.G12V mutated KRAS CRC cells), which was consistent with the observed mutational regression (p.G12V/p.G13D inprimary→p.G13D in metastatic tumor)." (PMID 35936004, 2022). "All but one patient in the KRAS wildtype group presented with de novo metastatic disease." (PMID 36209277, 2022). "Regardless of type and location, KRAS mutations play a prognostic role and, when grouped together, patients with KRAS mutated metastatic disease have a higher mortality rate (18.5% vs. 34%) and a shorter survival (14 months vs. 23.5 months) than wt ones." (PMID 35625772, 2022). "Interestingly, in all studies of pluri-metastatic disease the RAS mutation status of PT is maintained in the matched MT; by converse, in some cases KRAS mutations are exclusive events of metastases." (PMID 32332709, 2020). "Comparing our genetic patterns to the pluri-metastatic disease we focused on KRAS and SMAD4." (PMID 32332709, 2020). "Neither primary nor metastatic tumor harbored KRAS/BRAF mutations according to polymerase chain reaction using formalin-fixed paraffin-embedded tissues." (PMID 29960592, 2018). "Finally, we identified a population with KRAS‐mutated metastatic tumors that received treatment with EGFR antibodies prior to biopsy of metastatic site, based on a diagnosis of KRAS wild‐type in CRC primary performed outside our institution." (PMID 28618197, 2017).
metastatic disease (continued). "Among KRAS-tested patients, testing at the time of mCRC diagnosis increased annually from 27.4% in 2008 to 78.4% in 2011, corresponding to current recommendations that patients be KRAS-tested at diagnosis of metastatic disease to aid in informing their overall treatment plan." (PMID 25888436, 2015). "KRAS, NRAS, and BRAF mutations were always identical in both the primary and metastatic tumors." (PMID 25164765, 2014). "Anticipating KRAS testing before the onset of metastatic disease in patients at high risk does not affect the sustainability and cost-effectiveness profile of cetuximab in first-line mCRC." (PMID 24465771, 2014). "Cost effectiveness results of Early KRAS testing in high risk patients that would have no access to well-timed KRAS testing if they develop metastatic disease." (PMID 24465771, 2014). "Ultimately our results from a large dataset of patients with metastatic disease do not support loss of PTEN expression based on CNA as a prognostic marker in the overall population or any subgroups based on KRAS or BRAF mutation status." (PMID 23930204, 2013). "Using KRAS mutation analysis as a means to support site of origin of a metastatic tumor has not been previously reported." (PMID 23119210, 2012). "Of the 25 discordant cases, 12 patients had the KRAS mutation in the primary tumors, and not in the metastatic sites; 13 patients had the KRAS mutation in the metastatic tumors, and not in the primary tumors." (PMID 22876814, 2012). "In summary, the substantial discordance of KRAS and EGFR mutation status between primary tumors and metastatic tumors may have therapeutic implications for EGFR-targeted therapy strategy." (PMID 21414214, 2011). "For NSCLC patients with metastases, determining the KRAS and EGFR mutation status in both primary and metastatic tumors may be critical for making meaningful decisions regarding the appropriate use of targeted therapies." (PMID 21414214, 2011). "The metastatic disease treatment targeting EGFR is found to be efficient only if KRAS and BRAF are not mutated." (PMID 21103049, 2010). "Our results suggest that inhibition of TOPK could be beneficial for at least two groups of CRC patients together representing 30–40% of all cases, namely, those with a KRAS or BRAF mutation and those with metastatic disease supported by several factors." (PMID 19935791, 2010). "As a result, we could not perform a comparative analysis between primary and metastatic tumors, which represents a significant limitation in understanding potential differences in KRAS mutation prevalence between these tumor sites." (PMID 40282985, 2025). "Other explored variables, including gender, site of metastatic disease, the extent of metastatic disease, previous resection of the bowel cancer primary, and the number of lines of therapy did not have a significant influence on the benefit associated with EGFR mAb in patients in KRAS WT mCRC." (PMID 38402342, 2024). "However, it should be noted that KRAS could be an independent marker for metastatic disease in BRAFWT patients." (PMID 34877621, 2022). "However, mutation of KRAS and BRCA2 was found in both primary and metastatic tumors." (PMID 35666369, 2022). "Interestingly, the metastatic tumor in the RL, which consistently responded to panitumumab and showed no mutation by Sanger sequencing, revealed multiple KRAS mutations, Q61Ht, G12A and G12R, with indices higher than the cut-off values." (PMID 34840814, 2021). "In metastatic tumors, with one exception where no mutation was detected, only the KRAS c.34G > T; p.Gly12Cys mutation could be detected." (PMID 32560038, 2020). "In our study, although two of 11 patients showed a heterogeneous KRAS mutation status no case with discordance in the KRAS status between the primary and metastatic tumors had a clinical significance and thus represented no alteration in clinical decision-making." (PMID 33002027, 2020).
metastatic disease (continued). "The best approach to guide anti-EGFR treatment decision in SP-CRC with metastatic disease would be to test the metastatic tissue for KRAS and NRAS mutations, because it is not possible to be certain which primary SP-CRC lesion led to the metastasis without any additional study." (PMID 25859555, 2015). "Among 38 second line treated MCRC pts evaluated for KRAS genotype, 21 wild-type (55.3%) and 17 mutant (44.7%), demographic and baseline features were, respectively: male/female ratio, 17/4 and 8/9; metachronous/synchronous metastatic disease, 10/11 (48/52%) and 5/12 (29/71%) pts." (PMID 24247407, 2014). "Panelists agree that in patients with metachronous metastases this may be undoubtedly realized by anticipating KRAS test before the onset of metastatic disease, meeting the need of improving decision making in clinical practice, as it has been recently underlined." (PMID 24465771, 2014). "Therefore, the convergence of panelists opinion toward the anticipation of KRAS testing in order to ensure the timely use of the most appropriate and personalized therapy in metastatic disease means that an anti-EGFR therapy should be extensively considered in metastatic KRAS wt tumors." (PMID 24465771, 2014). "Patients diagnosed with mutant KRAS CRC have a poorer prognosis compared to those with wild-type KRAS CRC, particularly in the context of metastatic disease." (PMID 37504287, 2023). "The determination of KRAS, BRAF, and MSI status has become an indispensable step in therapeutic planning, especially in patients with metastatic disease." (PMID 31828035, 2019). "The mutational status between primary and metastatic tumors was usually concordant, but KRAS,HER2, and PIK3CAHS were significantly higher in metastatic tumors than in primary tumors." (PMID 29518290, 2018). "For example, the discordance of KRAS and BRAF mutations due to genetic diversification of metastatic cells compared to their primary tumor, may explain the lack of efficacy and the emergence of subsequent resistance when treating metastatic disease with EGFR monoclonal antibodies." (PMID 25902072, 2015). "Additionally, two KRAS-mutant URCCs and one KRAS-mutant PRCC developed metastases during the follow-up period, resulting in a total of 7 patients (41%) with metastatic disease." (PMID 41375035, 2025). "The literature data consistently show a negative prognostic impact of KRAS and BRAF mutations in MSI patients on long-term outcomes such as RFS and OS, emphasizing the adverse effects of these mutations in metastatic disease rather than in operable cases." (PMID 38786299, 2024). "The MAPK pathway showed mutations in the BRAF, KRAS, and MAP2K1 genes in three brain metastatic tumors that were not present in their breast primary tumors." (PMID 36507516, 2022). "The results showed that no statistical differences in the frequencies of EGFR, KRAS, HER2, BRAF, and PIK3CA mutations and other GMs were observed between unpaired primary and metastatic tumors." (PMID 29518290, 2018). "It is possible that patients with metastatic disease may refuse treatments such as anti-EGFR therapy, rendering KRAS status of little clinical value." (PMID 29202108, 2017).
metastatic disease (continued). "More importantly, patients diagnosed with widespread metastatic disease, or who were not candidates for surgical resection, often did not have tissue available for KRAS testing." (PMID 24788807, 2014). "In primary tumors lacking KRAS, NRAS, or BRAF mutations, we did identify occult alterations in the EGFR/RAS pathway that in some patients were private to the metastatic tumor." (PMID 25164765, 2014). "Our previous reports of significantly different clinical outcome of L-L compared to multiple metastatic disease, particularly in KRAS wild-type patients, while not in KRAS mutant, were confirmed in young-elderly patients and should be prospectively verified." (PMID 24307987, 2013). "Majority of the discordant cases in our study showed KRAS and EGFR mutations in the metastatic tumors rather than in their corresponding primary tumors." (PMID 21414214, 2011). "Newer models that express cancer-initiating oncogenes, such as KRAS and its downstream effector c-MYC in a ligand-controlled manner, provided additional insight into the significance of these oncogenic drivers in premalignant lesions as well as primary and metastatic tumors in vivo." (PMID 34491463, 2021). "At the same time, transplantation of merely 200–500 KRAS intact cells resulted in the formation of primary and metastatic tumors with a median animal survival of three weeks, whereas none of the KRAS KO cell lines were capable of developing tumors under these conditions after 3 months." (PMID 33674596, 2021). "However, higher HS values of KRAS, HER2, and PIK3CA were observed in metastatic tumors than in unpaired primary tumors, and heterogeneity between primary and metastatic tumors in copy‐number alterations may partly contribute to the differences." (PMID 29518290, 2018). "Computationally, this is equivalent to adding to the population of patients eventually developing metastatic disease and being treated, the cost of KRAS tests of the population of patients that will not develop metastases and for which the test will not be necessary." (PMID 24465771, 2014). "Moreover, while for metastatic disease, CMS4 tumors are resistant to anti-EGFR therapies (irrespective of KRAS mutational status) and to doublet/triplet backbone chemotherapy, the benefit of adjuvant treatment for early and locally advanced CMS4 tumors is not obvious." (PMID 34201502, 2021). "However, in that study, a major difference in KRAS activation between the primary and metastatic tumors could have been masked by the absence of related primary and metastatic samples." (PMID 20020061, 2009). "Similarly, our study found that the frequencies of EGFR, KRAS, HER2, BRAF, and PIK3CA mutations in TKI‐naive samples and the frequencies of sensitizing EGFR and T790M mutations in TKI‐relapsed samples showed no statistical differences between unpaired primary and metastatic tumors." (PMID 29518290, 2018). "Conversely, in KRAS mutant MCRC pts, median PFS and OS were not significantly affected by the extension of metastatic disease (L-L compared to O/MM)." (PMID 23497191, 2013).